CAMK2B (calcium/calmodulin dependent protein kinase II beta)
Diseases named in the same sentence as CAMK2B in open-access papers (continued):
Sharing a sentence is not in itself a finding about the gene and the disease.
type 2 diabetes (4 papers, 2018 to 2023). "SNPs in CAMK2B have been consistently linked to birthweight and risk of type 2 diabetes in different populations." (PMID 37612641, 2023). "In another study, allele-specific expression of several genes in islets (ANPEP, CAMK2B, HMG20A, KCNJ11, NOTCH2, SLC30A8 and WFS1) showed that even subtle changes of gene dosage may have significant consequences for development of type 2 diabetes." (PMID 30497374, 2018).
cardiac hypertrophy (3 papers, 2016 to 2025). "Specifically, markers of non-cardiac differentiation, such as those for vascular endothelium (VWF) and non-cardiac muscle (CDH6, CNN2 and MYLK) were downregulated, while genes encoding for cardiac hypertrophy (IGF1R) and calcium handling (CAMK2B) were upregulated." (PMID 26785135, 2016).
diabetes (3 papers, 2021 to 2022). "For example, variants proximal to Camk2b have been associated with numerous traits in humans, including diabetes." (PMID 34849860, 2021). "Among these differentially expressed mRNAs in exosomes, CAMK2B has been found to be overexpressed in the liver of STZ-induced male diabetic mice and is involved in the pathogenesis of diabetes." (PMID 33714195, 2021).
leukemia (3 papers, 2018 to 2021). A malignant (clonal) hematologic disorder, involving hematopoietic stem cells and characterized by the presence of primitive or atypical myeloid or lymphoid cells in the bone marrow and the blood. "Specifically, CAMK2B, one of the top 5% of genes associated with BCR-ABL1 in our prediction, is a target of cyclosporin A, which can sensitize BCR-ABL-positive leukemia to BCR-ABL inhibitors." (PMID 30040819, 2018).
liver cancer (3 papers, 2021 to 2026). An epithelial or non-epithelial malignant neoplasm that arises from the liver. "Notably, CAMK2B showed medium expression in both normal and liver cancer tissues, while CDC20 and PPP1CA were undetected in normal tissue but exhibited medium expression in liver cancer." (PMID 41511815, 2026).
Cachexia (2 papers, 2010 to 2019). Severe weight loss, wasting of muscle, loss of appetite, and general debility related to a chronic disease. "Finally, we found drugs targeting MSTN, CXCL12, and CAMK2B, which may be considered for the development of novel therapeutic strategies for cancer-related cachexia." (PMID 31013615, 2019).
developmental delay (2 papers, 2014 to 2022). "Here we report the detailed description of a child with a de novo gain of function (GoF) mutation in the gene Ca/Calmodulin dependent protein kinase 2 beta (CAMK2B c.328G > A p.Glu110Lys) who presents with developmental delay and periodic neuropsychiatric episodes." (PMID 35620293, 2022).
hypertrophic cardiomyopathy (2 papers, 2022 to 2023). A condition in which the myocardium is hypertrophied without an obvious cause. "To this end, we conducted gene enrichment analysis, and observed stronger enrichments of upregulated genes involved in hypertrophic cardiomyopathy (ADRA1A, TNNI3, MYL2) and cardiac muscle contraction (CACNA1C, CASQ2, CAMK2B)." (PMID 37084237, 2023). "Next, our KEGG analysis showed that transcripts up-regulated in the mutant cardiomyocytes were related to hypertrophic cardiomyopathy (ACTC1, MYL2, MYL3), Ca2+-dynamics regulatory pathway (ATP2B4, CACNA1C, CAMK2B, PLN), as well as cardiac-muscle contraction transcripts (ACTC1, MYH7, TNNI3, TNNT2)." (PMID 35784482, 2022).
psoriasis (2 papers, 2022 to 2025). An autoimmune condition characterized by red, well-delineated plaques with silvery scales that are usually on the extensor surfaces and scalp. "CAMK2B expression was reduced in the imiquimod-induced psoriasis mouse model, which confirmed that the SDS-induced thickening of the stratum corneum in the 3D skin model was correlated with CAMK2B expression." (PMID 41465207, 2025).
acute lymphoblastic leukemia (1 paper, 2022). Leukemia with an acute onset, characterized by the presence of lymphoblasts in the bone marrow and the peripheral blood. "Two replicated CpGs, located on genes NAV2 and CAMK2B, had been related to childhood acute lymphoblastic leukemia in a previous study." (PMID 36266660, 2022).
atherosclerosis (1 paper, 2022). A disease characterized by the build-up of fatty material and calcium deposition in the arterial wall resulting in partial or complete occlusion of the arterial lumen. "A total of 6 genes were enriched in the lipid and atherosclerosis signaling pathway (CAMK2B, VAV3, PLCB3, NFATC3, TNFRSF10B, and BCL2L1), and these genes were regulated by tRF-60:76-Val-AAC-1-M5." (PMID 36247465, 2022).
Cirrhosis (1 paper, 2022). A chronic disorder of the liver in which liver tissue becomes scarred and is partially replaced by regenerative nodules and fibrotic tissue resulting in loss of liver function. "Therefore, cirrhosis mouse models with a blood vessel-rich background should be established to further elucidate the relationship among CAMK2B, fibroblasts, and vascular endothelial cells." (PMID 35127542, 2022).
Hypertension (1 paper, 2024). The presence of chronic increased pressure in the systemic arterial system. "The results revealed a cluster of proteins, including the SRC family, CAMK2B, CAMK2D, TEC, GSK3, VAV, and RAC, which were markedly upregulated in patients with hypertension compared to those with prehypertension (fold change ≥ 1.6 or ≤−1.6, area under the curve ≥ 0.8, and q-value < 0.05)." (PMID 38732116, 2024).
sarcoidosis (1 paper, 2025). Sarcoidosis is a multisystemic disorder of unknown cause characterized by the formation of immune granulomas in involved organs. "Among the twelve common DEGs, SALL4, WNT10A, RASAL1, CAMK2B were significantly upregulated while GADD45B, KLF4, OLR1, CSF3, WIF1, RAMP3 and AGER downregulated in both sarcoidosis and LC as compared to the controls." (PMID 40797277, 2025).
Sensory neuropathy (1 paper, 2020). Peripheral neuropathy affecting the sensory nerves. "They propose a dynamic model for FAM134B protein oligomerization and ER membrane scission, which are driven by CAMK2B‐mediated phosphorylation of the receptor and are altered in sensory neuropathy." (PMID 32073155, 2020).
Stroke (1 paper, 2018). Sudden impairment of blood flow to a part of the brain due to occlusion or rupture of an artery to the brain. "We further aimed to assess the potential role of CKB, CaMK2B, CaMK2D, CaMK2A and CMPK as biomarkers of stroke." (PMID 29784938, 2018). "Further exploration of these candidates in human plasma revealed the potential of CKB and CMPK to diagnose stroke, while CaMK2B and CMPK resulted feasible biomarkers of functional stroke outcome." (PMID 29784938, 2018). "Notably, CaMK2B, but not CaMK2A neither CaMK2D, appeared as a valuable indicator of stroke patient functional outcome." (PMID 29784938, 2018).
tauopathy (1 paper, 2019). Neurodegenerative disorders involving deposition of abnormal tau protein isoforms (tau proteins) in neurons and glial cells in the brain. "While this result does not demonstrate a direct role for TIA1 in mediating alternative splicing of Gria2, Snap25, or Camk2b, the results indicate that normalization of splicing represents a clear component of the neuroprotection provided by TIA1 reduction in tauopathy." (PMID 31875547, 2019).
viral infections (1 paper, 2021). "Here, viral infections with both HSV-1 and HSV-2 significantly decreased the gene expression of CAMK2B in cortical neurons." (PMID 34696502, 2021).
cancer (27 papers, 2010 to 2025). A tumor composed of atypical neoplastic, often pleomorphic cells that invade other tissues. "Based on an integrative meta-analysis, CAMK2B was found to be associated with the development of cancer cachexia." (PMID 31827401, 2019). "Notably, PTPN1, TRIM46, TRIM17, FCGR1A, IRF5, IRF6, and CAMK2B had a higher frequency of gain mutations in most human cancer types." (PMID 37941546, 2023). "This approach leverages the established clinical use of MAPK kinase inhibitors in the treatment of certain cancers, providing a solid foundation for potential therapeutic applications targeting CAMK2B-related pathways." (PMID 41050075, 2025). "We detected lower levels of lncRNA GUSBP11 (P=0.0618) and CAMK2B (p=0.0447) in tumor tissue samples than in the normal tissue adjacent to the carcinoma, whereas levels of miR-432-5p were found to be higher in tumor tissue (P=0.0097)." (PMID 35127542, 2022). "Notably, these inhibitors can block the signal cascade and inhibit the pro-cancer signals transmitted from CAMK2B to tumor cells." (PMID 41050075, 2025). "However, only a few studies have focused on the role of CAMK2B in cancer." (PMID 40836964, 2025). "Additionally, the negative correlation between expression of CAMK2B and endothelial cells (R=-0.455) and cancer-associated fibroblast (R=-0.384) was confirmed using Xcell and EPIC." (PMID 35127542, 2022). "Finally, we found drugs targeting MSTN, CXCL12, and CAMK2B, which may be considered for the development of novel therapeutic strategies for cancer cachexia." (PMID 31013615, 2019). "When the DEGs were further compared across four cancer types, we found five coregulated DEGs (upregulated DEGs: PCSK1N, CAMK2B, RUNDC3A and SNAP25; downregulated DEG: DPT) among four NECs." (PMID 35752613, 2022). "CAMK2B is expressed in neural tissues and CAMK2D in heart and skeletal muscles with little information on cancers." (PMID 32483123, 2020). "We found several overlapping DEmRNAs that were involved in multiple pathways, such as SLC8A1, CAMK2B, and CACNA2D1, and have been demonstrated to play important roles in cancer pathogenesis." (PMID 31827401, 2019). "Additionally, CAMK2B is present in epithelial-mesenchymal transition (EMT).Currently, emerging technologies have been applied to improve cancer diagnosis." (PMID 41050075, 2025). "VEGF and TGFβ1 have shown positive correlation with cancer, and the expression of both are negative correlated with CAMK2B, suggesting they also act as downstream effectors of CAMK2B in KIRP." (PMID 35127542, 2022). "In our study, five DEPs (CD44, Stat3, CAMK2D, CAMK2B and CAMK2G) were identified in the proteoglycans in cancer signaling pathway, which worked together to modulate functions of this pathway, such as cell migration and invasion, cell adhesion, cell growth and survival." (PMID 36678534, 2022). "Cancer and organismal injuries were the top two diseases and function categories that were predicted to increase, along with neurological (HAND2), hepatic system (APOE, CACNG4, CAMK2B), respiratory system (WNT16), and skeletal muscle developmental disorders (ADD2, HAND2)." (PMID 39508990, 2025).
tumor (26 papers, 2009 to 2025). "High expression of CAMK2B was also found to be associated with lower tumor grade (P=0.0328) and low metastasis (P=0.0375)." (PMID 35127542, 2022). "High CAMK2B mRNA expression was associated with worse overall and distant metastasis free survival in estrogen receptor positive (ER) tumours (p = 0.00077 and p = 0.0341, respectively)." (PMID 27605043, 2016). "In nude mouse models, diminished subcutaneous tumor growth was observed in mice injected with SK-RC-39 cells stably overexpressing CAMK2B (P=0.0351) as compared to mice injected with SK-RC-39 control cells." (PMID 35127542, 2022). "Consistent with this, reduced expression of Camk2a and Camk2b was validated in different EμMyc/Casp2−/− tumor samples." (PMID 30670683, 2019). "Thus, in this study, we show that the TME determines prognosis of KIRP patients via the core effector molecule CAMK2B, which mediates both microenvironmental remodeling and tumor progression." (PMID 35127542, 2022). "Indeed, we found that protein levels of CAMK2B are lower in tumor tissue than in paired tumor-adjacent tissue (P=0.0227)." (PMID 35127542, 2022). "Notably, tumor-suppressive roles have been reported for CAMK2B, EGR3, NPAS2, PCDH8, and RGS6." (PMID 39796709, 2024). "Similarly, high expression of CAMK2B mRNA is associated with no metastasis (P = 0.002), early-stage disease (P=0.0299), and small tumor size (P=0.0226)." (PMID 35127542, 2022). "For example, tumours from patients in cluster 1 (n = 11) had significantly more mutations (8.6 vs 3.5 in all other groups) and a significant enrichment of mutations and amplifications in genes from the ERBB signalling pathway (PLCG2, MAP2K7, ERBB4, and CAMK2B)." (PMID 33862582, 2021). "For instance, the upregulation of WNT10A, RASAL1, CAMK2B, and SALL4 suggests their involvement in tumor-promoting processes, such as cell proliferation, migration, and immune evasion." (PMID 40797277, 2025). "Data validation in tissue samples confirmed that levels of CAMK2B and GUSBP11 were lower, while those of miR-432-5p were higher in tumor tissue than in paired tumor-adjacent tissue, suggesting a protective role of the axis in pRCC." (PMID 35626699, 2022). "Here, to evaluate the precise function of CAMK2B, we stably overexpressed and silenced CAMK2B expression in a KIRP cell line and found that upregulation of CAMK2B inhibits both proliferation and tumor stromal cell infiltration in vivo and in vitro." (PMID 35127542, 2022). "The analysis of the corresponding tumor and non-tumor samples also revealed upregulation of COMP, matrix proteins such as COL5A1, COL11A1, and FN1, and genes of the Wnt pathway (WNT7B, FZD10, SFRP2), while PLCB1, CAMK2B, PLCB4 and WIF1 are downregulated." (PMID 33227073, 2020).
neurodevelopmental disorder (8 papers, 2020 to 2025). A behavioral and cognitive disorder with onset during the developmental period that involves impaired or aberrant development of intellectual, motor, or social functions. "In addition, in the paralogous isoform CAMK2B, P213L mutation, which is in the same position as P212L in CAMK2A, has been found in a patient with neurodevelopmental disorders." (PMID 36117912, 2022).
infection (7 papers, 2015 to 2025). The state of being infected such as from the introduction of a foreign agent such as serum, vaccine, antigenic substance or organism. "Given the functional similarities between CAMK2A and CAMK2B, the presence of CAMK2B in this study points to its potential involvement in rabies pathogenesis, particularly during the early phases of infection when neuronal communication is first disrupted." (PMID 41441337, 2025). "However, one or more of these proteins, such as CAMK2B, involved in transcriptional regulation, might be implicated in future studies to determine the mechanism for HLA-homozygous lymphocyte resistance to the infection." (PMID 32831108, 2020). "We have previously linked mRNA expression of both CAMK2B and ARC to synaptic function in our cell model and, interestingly, here both HSV-1 and HSV-2 decreased CAMK2B and ARC mRNA expression in cortical neurons 48 h post-infection." (PMID 34696502, 2021). "The expression of CAMK2B, GPX3, and SOD2 in the infection + NAC group was lower than that in the infection group (p < 0.05)." (PMID 38149012, 2023).
neurological disorders (4 papers, 2018 to 2023). "We thus expect that single-nucleotide polymorphisms or other mutations that modulate CAMK2B, and potentially CAMK2A, alternative splicing alter CAMK2 functionality and may be involved in a variety of neurological diseases." (PMID 36543542, 2023).
neurodegenerative disease (3 papers, 2016 to 2024). A disorder of the central nervous system characterized by gradual and progressive loss of neural tissue and neurologic function. "These include key members of the post-synaptic proteome functional, structural and regulatory components (e.g. Dlg4, Fyn, Arc, CamK2b) as well as genes with known associations with neurodegenerative disease (tau)." (PMID 27069252, 2016).
CAMK2B also shares sentences with these, for which no sentence is quoted: Cognitive impairment (4 papers); colorectal cancer (4); gastric cancer (4); prostate carcinoma (4); Alzheimer disease (3); Arrhythmia (3); colon cancer (3); Anxiety (2); brain diseases (2); Cerebral ischemia (2); ischemia (2); ischemic stroke (2); neuroblastoma (2); ovarian carcinoma (2); pancreatic cancer (2); triple-negative breast carcinoma (2); alcohol withdrawal syndrome (1); amyotrophic lateral sclerosis (1); brain tumor (1); cardiac arrhythmia (1); cardiac ischemia (1); chronic myeloid leukemia (1); cocaine abuse (1); cognitive decline (1); dementia (1); drug dependence (1); gastric adenocarcinoma (1); glaucoma (1); Glucose intolerance (1); heart failure (1).
A further 20 diseases each share a sentence with CAMK2B in 1 paper.